RNU1-73P (RNA, U1 small nuclear 73, pseudogene)
Gene: Small nuclear RNA gene on chromosome 5 (97,175,950 to 97,176,113, reverse strand). Ensembl gene ENSG00000206698.
Homologues: Orthologues: chimpanzee U1 (100% identical), macaque U1 (88% identical). Paralogues in human: RNVU1-32 (79% identical), RNU1-89P (78% identical), RNU1-1 (77% identical), RNU1-2 (77% identical), RNU1-27P (77% identical), RNU1-28P (77% identical), RNU1-3 (77% identical), RNU1-4 (77% identical), RNVU1-1 (77% identical), RNVU1-18 (77% identical), RNVU1-29 (77% identical), RNVU1-31 (77% identical), and 134 more.